CSMD1 (CUB and Sushi multiple domains 1)
Description:
Potential suppressor of squamous cell carcinomas.
Synonyms: KIAA1890; PPP1R24
Tractability: Antibody: UniProt predicts a signal peptide or a membrane-spanning region. PROTAC: its protein half-life has been measured.
Gene: Protein-coding gene on chromosome 8 (2,935,353 to 4,994,972, reverse strand). Ensembl gene ENSG00000183117.
Subcellular location: Membrane
Subcellular location (Human Protein Atlas): Vesicles
Gene Ontology:
Molecular function: protein binding
Cellular component: membrane
Genetic constraint (gnomAD): Loss-of-function variants: 163 observed, 316.96 expected, observed/expected ratio (o/e) 0.51, 90% interval 0.45 to 0.59. The synonymous counts are far from expectation, so gnomAD's model fits this gene poorly and the ratio says little. Missense variants: 6,266 observed, 4,090 expected, observed/expected ratio (o/e) 1.53, 90% interval 1.5 to 1.56. Synonymous variants: 2,604 observed, 1,599 expected, observed/expected ratio (o/e) 1.63, 90% interval 1.58 to 1.68.
Homologues: Orthologues: chimpanzee CSMD1 (99% identical), macaque CSMD1 (99% identical), dog CSMD1 (95% identical), rat Csmd1 (94% identical), mouse Csmd1 (93% identical), guinea pig CSMD1 (93% identical), pig CSMD1 (82% identical), tropical clawed frog csmd1 (76% identical). Paralogues in human: CSMD2 (65% identical), CSMD3 (63% identical), SVEP1 (22% identical), CR1 (11% identical), CR2 (8% identical), SEZ6L (6% identical), SEZ6 (6% identical), CFH (6% identical), SELP (6% identical), PAPPA2 (6% identical), SEZ6L2 (6% identical), PAPPA (5% identical), and 27 more.
Diseases named in the same sentence as CSMD1 in open-access papers:
CSMD1 is named in the same sentence as 127 diseases in open-access papers, as found by Europe PMC text mining. Sharing a sentence is not in itself a finding about the gene and the disease. The quoted sentences say what the papers report.
schizophrenia (71 papers, 2012 to 2025). A major psychotic disorder characterized by abnormalities in the perception or expression of reality. "CSMD1, a transmembrane protein involved in various cellular processes, is highly expressed in the brain and linked to diseases like cancer, lupus, and schizophrenia." (PMID 40725187, 2025). "It is worth mentioning that, despite CSMD1 having been described as a candidate susceptibility gene for schizophrenia, its specific role in neurodevelopmental disorders is unclear." (PMID 40362533, 2025). "While intronic variants of CSMD1 have previously been associated with schizophrenia, biallelic exonic variants have been linked to neurodevelopmental disorders." (PMID 40362533, 2025). "Several studies highlight the potential role of CSMD1, which is considered a statistically strong risk factor for schizophrenia." (PMID 40362533, 2025). "CSMD1 encodes a large membrane-bound protein and was associated with various biological processes and conditions, including schizophrenia, the complement system, cancer, metastasis and cell migration." (PMID 40771400, 2025). "One recent and stringent example comes from the observations that common variation within CSMD1, which encodes a putative complement inhibitor, has consistently associated with schizophrenia at genome-wide significance." (PMID 35963926, 2022). "Further, CSMD1 has also been implicated in schizophrenia (The Schizophrenia Psychiatric Genome-Wide Association Study Consortium, 2011), bipolar disorder and cognitive function (Norwegian/Scandinavian cohort)." (PMID 34177453, 2021). "CSMD1 has been associated with behavioural disinhibition, schizophrenia, cognitive tests, chronic bronchitis, and bipolar disorder." (PMID 34384432, 2021). "Neurophysiological deficits have been observed in CSMD1 depleted mice, inducing blunted emotional responses, anxiety and depression, and it has also been linked to schizophrenia." (PMID 33218114, 2020). "CSMD1 is highly expressed in the CNS and its schizophrenia risk allele was associated with poor performance on neuropsychological measures of general cognitive ability and memory function." (PMID 32116493, 2020). "The single-nucleotide polymorphisms (SNPs) in the CUB and Sushi multiple domains-1 (CSMD1) gene were recently identified in genome-wide association studies (GWAS) as significant genetic markers for schizophrenia (SZ) and cognitive performance." (PMID 29379655, 2017). "Among these five novel schizophrenia risk genes, we focused on Cnnm2, Csmd1, and Mmp16 in this study." (PMID 29163023, 2017). "Further, it has been reported that genetic variation of CSMD1 (Schizophrenia Psychiatric Genome-Wide Association Study [GWAS] Consortium, 2011) plays a role in the ratio between DA and serotonin metabolites in CSF." (PMID 29163023, 2017). "Recently, genetic markers rs10503253 and rs2616984 in the CUB and Sushi multiple domains-1 (CSMD1) gene have been reported to be associated with schizophrenia and cognitive functions in genome-wide association studies." (PMID 29379655, 2017). "A common intronic CSMD1 variant, rs10503253, was reported as genome-wide significant for SZ by Schizophrenia Psychiatric Genome-Wide Association Study Consortium and was subsequently replicated in other GWA and meta-analysis studies." (PMID 29379655, 2017). "For example, the CUB and Sushi multiple domains-1 gene (CSMD1) has been associated with increased risk for both schizophrenia and cannabis dependence." (PMID 28680405, 2017). "Concerning composing, we also found suggestive evidence for joint linkage and LD at CSMD1 intron (rs4242493, p-value 2.0x10-6), a locus that is also associated with schizophrenia." (PMID 26909693, 2016). "An intergenic SNP (rs183854424) 14 kb downstream of CSMD1, which is implicated in schizophrenia, showed suggestive evidence of association in the WM FA meta-analysis (meta P value = 1.43 × 10−07) and the multimodal analysis (Fisher P value = 1 × 10−07)." (PMID 26852023, 2016).
schizophrenia (continued). "A CSMD1 intron 3 SNP displays p < 10-8 association with schizophrenia and more modest associations with individual differences in performance on tests of cognitive abilities." (PMID 26171607, 2015). "Immune and inflammatory processes were implicated in schizophrenia and depression comorbidity by a number of models, including Csmd1, db/db, GSK-3, and MIA." (PMID 25762938, 2015). "CSMD1, which has also been associated with schizophrenia, is a complement control-related gene, and supports the theory of diminished activity of immunity-related pathways in the brain as a disease mechanism for psychiatric disorders including BD." (PMID 24387768, 2014). "In two accompanying papers, five schizophrenia susceptibility genes including CSMD1, C10orf26, CACNA1C, TCF4, and ZNF804A were validated as miR-137 targets, providing additional evidence for the involvement of miR-137 in schizophrenia." (PMID 25250332, 2014). "In parallel, the Psychiatric Genome-Wide Association Study (GWAS) Consortium (PGC) identified CSMD1 as one of only seven verified loci in a large schizophrenia GWAS-based meta-analysis involving about 18.000 patients and 34.000 controls." (PMID 24244513, 2013). "Recent meta-analyses of schizophrenia genome-wide association studies (GWASs) have identified the CUB and SUSHI multiple domains 1 (CSMD1) gene as a statistically strong risk factor." (PMID 24244513, 2013). "A subsequent GWAS replicated this finding, demonstrating a significant association between schizophrenia and an intronic SNP in CSMD1." (PMID 23284669, 2012). "Also, a newly discovered complement C3 and C4 regulator, CUB and Sushi multiple domains 1 (CSMD1), has been placed among the top of genome-wide risk alleles for schizophrenia." (PMID 39022733, 2024). "Also, it is worth exploring the effect of other immune-related players in the complement pathway (e.g., CSMD1, C1q, C3) on suicide risk in schizophrenia patients." (PMID 38341430, 2024). "Several genetic studies reported that CSMD1 was associated with schizophrenia." (PMID 37511534, 2023). "Initially, the CSMD1 gene was proven to be associated with schizophrenia (SZ), though CSMD1 is involved in many different mechanisms in the body with the discovery of its roles in the complement system, cancer, metastasis, cell migration, and epithelial–mesenchymal transition (EMT)." (PMID 36553598, 2022). "Moreover, CSMD1 has been associated with post-traumatic stress disorder, schizophrenia, and bipolar disorders." (PMID 35836289, 2022). "Variants in CSMD1 have been associated with deleterious effects across a number of neurological and neuropsychiatric phenotypes (see the Supplementary): autism, bipolar disorder, Alzheimer’s disease, Parkinson’s disease and schizophrenia." (PMID 35162247, 2022). "Interestingly, in our study, this gene was implicated through markers associated with a measure of working memory; a study of this gene reported that a schizophrenia risk variant in CSMD1 was associated with spatial working memory." (PMID 36457050, 2022). "For example, microglia showed a reduced expression of Csmd1, a complement regulatory gene linked to familial epilepsy and schizophrenia (Schizophrenia Psychiatric Genome‐Wide Association Study & C, 2011), and of the protocadherin Pcdh9, which is a risk factor for major depressive disorder." (PMID 33644903, 2021). "An allele of the complement inhibitor, CSMD1, is also associated with schizophrenia." (PMID 34552056, 2021). "Also linked to schizophrenia is a common intronic allele of the CSMD1 gene, which encodes a complement inhibitor expressed in neural tissue, including developing neurons." (PMID 34552056, 2021). "A wide range of previous studies have confirmed an association of CSMD1 with schizophrenia." (PMID 33384710, 2020). "For example, the locus containing CSMD1 is associated with schizophrenia in the GWAS Catalog." (PMID 31292438, 2019).
schizophrenia (continued). "However, CSMD1 has also been associated with autistic spectrum disorders and schizophrenia and is a known target of mir-137, a microRNA that regulates neuronal maturation and adult neurogenesis." (PMID 27716277, 2016). "CSMD1 is a tumor-suppressor gene associated with psoriasis, Kawasaki disease and schizophrenia." (PMID 25927497, 2015). "However, little reported data links specific human CSMD1 genomic variants to specific molecular or behavioral phenotypes relevant to particular aspects of addiction or schizophrenia." (PMID 26171607, 2015). "The observation of anxiety- and depression-like behaviors in Csmd1 KO mice may also provide one example supporting the notion of shared genetic susceptibility across schizophrenia, bipolar disorders and major depression." (PMID 24244513, 2013). "Human genetic studies have implicated CSMD1 in schizophrenia." (PMID 23284669, 2012). "Precisely how CSMD1 variants predispose to schizophrenia is unknown." (PMID 38505993, 2024). "The mechanisms by which CSMD1 variants may influence drug dependence liability are unknown and likely to be a part of broader effects on brain function as CSMD1 markers have been associated with schizophrenia, autism, bipolar disorder, and general cognitive ability and executive function." (PMID 29675039, 2018). "The schizophrenia risk gene CUB and sushi multiple domains 1 (CSMD1) was the longest CDS we amplified at 10,838 nt, encompassing 70 coding exons." (PMID 40988056, 2025). "CSMD1 codes for a brain-expressed, complement inhibitor that has been implicated in ASD and schizophrenia most likely through the effects of the complement system on synaptic remodeling." (PMID 40894167, 2025). "In fact, low expression levels of CSMD1 have been detected in peripheral blood mononuclear cells in individuals with schizophrenia, in comparison to healthy controls." (PMID 40362533, 2025). "In contrast, a more limited enrichment was found for “Schizophrenia symptom severity measurement” (p = 0.0003), with only three genes displaying significant associations (RBFOX1, CSMD1, and TENM2)." (PMID 39237719, 2025). "Reduced PBMC expression of CSMD1 in people with schizophrenia was reported in a small Han Chinese cohort." (PMID 38505993, 2024). "CSMD1 has been linked to several diseases, such as cancer, Parkinson’s disease, and schizophrenia, indicating that CSMD1 dysfunction has various clinical effects." (PMID 37511534, 2023). "In family 1, with singleton schizophrenia, we detected four rare variants in genes implicated in schizophrenia, including p.Arg1627Trp of LAMA2, p.Pro1338Ser of CSMD1, p.Arg691Gly of TLR4, and Arg182X of AGTR2." (PMID 37511534, 2023). "Further, mRNA and protein levels of the CSMD1 were significantly lower in the peripheral blood in schizophrenia, compared with controls." (PMID 37511534, 2023). "Most strikingly, we found that both DMP (such as CSMD1) and DMRs (DAXX and ARL4D) are annotated to genes related to neurological disorders such as ASD, PTSD and schizophrenia, pointing out to the potential risk of these children to suffer from these disorders." (PMID 35836289, 2022). "Examples are CSMD1 in 8p23.2, a dosage-sensitive gene associated to ASD, schizophrenia and epilepsy and FBXO25, recently associated to neuropsychiatric disorders." (PMID 33925474, 2021). "CUB and sushi multiple domains 1 (CSMD1) is a complement control-related gene that inhibits the activation of complement C3 and has a possible role in lupus erythematosus and schizophrenia." (PMID 32183058, 2020). "CSMD1 plays a significant role in the etiology of schizophrenia and was reported to express in frontal-temporal and hippocampal regions of the brain by hierarchical bi-clustering analysis." (PMID 30341038, 2018). "In the Japanese population, some of these loci (MHC region, CSMD1, GRM7) have been associated with schizophrenia but the majority of current candidate loci have yet to be fully characterized." (PMID 28855529, 2017).
schizophrenia (continued). "This lncRNA has been shown to modulate expression of genes involved in schizophrenia such as CSMD1 and DISC1." (PMID 27913161, 2017). "Because, risk variants of CNNM2, CSMD1, and MMP16 are suggested to be involved in one of symptoms of schizophrenia, cognitive impairment." (PMID 29163023, 2017). "Here, we examined alteration in the novel schizophrenia risk genes, CNNM2, CSMD1, and MMP16 in the brains of rats undergoing cesarean section with or without global hypoxia." (PMID 29163023, 2017). "This is supported by fact that knocking out the immune molecule Csmd1 led to the development of glucose tolerance as well as schizophrenia and depression endophenotypes in mice." (PMID 25762938, 2015). "Human genetic studies have found significant links between CSMD1 and schizophrenia, with nominally significant links reported for depression and bipolar disorder." (PMID 25762938, 2015). "This suggests that Csmd1 was directly responsible for the manifestation of schizophrenia and depression-like behavior in these mice." (PMID 25762938, 2015). "CSMD1 has also been identified by several analyses of GWAS data and/or candidate gene studies for vulnerability to schizophrenia and clusters of schizophrenic symptoms." (PMID 26171607, 2015). "Future studies should determine if treating metabolic deficits in models such as the Csmd1-KO and db/db mice rescues schizophrenia and depression-related endophenotypes." (PMID 25762938, 2015). "Interestingly, previous pursuit of this cohort identified one hypo-methylated CpG, cg05306225 in newborns saliva that was annotated to the schizophrenia-related CSMD1 gene." (PMID 40188313, 2025). "Some of the most common traits and conditions associated with variation in the CSMD1 (The Cub and Sushi Multiple Domains 1) gene are PHF-tau measurement, schizophrenia, age at menarche, adolescent idiopathic scoliosis, neurofibrillary tangles measurement, chronotype measurement, and BMI." (PMID 38421723, 2024). "CSMD1 is also one of the genes shared by several major psychiatric disorders such as schizophrenia, bipolar disorder, major depressive disorder, autism spectrum disorder, attention deficit hyperactivity disorder, anxiety disorder, and posttraumatic stress disorder." (PMID 37511534, 2023). "It was also suggested that CSMD1 increased the risk of schizophrenia as a result of the negative effects of the A allele in CSMD1 rs10503253 on brain activity." (PMID 36553598, 2022). "The most significant gene in the genescore analysis, CSMD1 (CUB and sushi domain-containing protein 1), is highly expressed in the CNS, particularly in the frontal cortex and has been associated with schizophrenia." (PMID 33218114, 2020). "In addition, it is noteworthy that decreased expression of CSMD1, which codes for an inhibitor of the classical complement pathway, was observed in serum from patients with schizophrenia." (PMID 32116493, 2020). "Here, we investigated the schizophrenia risk genes, CNNM2, CSMD1, and MMP16 (Schizophrenia Psychiatric Genome-Wide Association Study [GWAS] Consortium, 2011), and identified alterations in gene expression in the asphyxia rat model for schizophrenia." (PMID 29163023, 2017). "The combined data thus support roles for common level-of-expression CSMD1 variation in a drug reward phenotype relevant to addiction and in cognitive differences that might be relevant to schizophrenia." (PMID 26171607, 2015). "The SNP whose variants are most studied for association with schizophrenia and individual differences in cognitive function, rs10503253, fails to display significant association with levels of CSMD1 mRNA expression." (PMID 26171607, 2015). "Therefore, we investigated the role of Csmd1 in behaviors modeling aspects of schizophrenia in mice." (PMID 23284669, 2012).